CD4 (CD4 molecule)
Diseases named in the same sentence as CD4 in open-access papers (continued):
Sharing a sentence is not in itself a finding about the gene and the disease.
Cryptococcal meningitis (continued). "In the subset of newly identified PLWH with a CD4 100–200 cells/mm3 in South Africa, serum CrAg positivity was observed in almost 2% of participants, and a positive CrAg result was strongly associated with an increased risk of cryptococcal meningitis or death during a 12-month follow-up period." (PMID 31959112, 2020). "Annually, 152,000 cases of cryptococcal meningitis are estimated to occur among people living with HIV (PLWH) with CD4 count <200cells/mm3 globally." (PMID 39854376, 2025). "Despite ART-mediated HIV-1 control (viral load < 20 copies/mL), CD4 count remained low (75/mm3) and recurrent episodes of cryptococcal meningitis were reported." (PMID 41290877, 2025). "Patients with cryptococcal meningitis who have elevated levels of CSF soluble cytokines, chemokine and immune checkpoint elements, CSF leukocytes and circulating CD4+ and CD8+ T cell responses have lower fungal burden and high probability of survival." (PMID 39928682, 2025). "We report a unique case of unilateral eyelid ptosis as the initial clinical sign of cryptococcal meningitis in an HIV-positive patient with a CD4+ T-cell count above 200 cells/μL." (PMID 41209902, 2025). "This case highlights an atypical presentation of cryptococcal meningitis, with CD4+ count above 100 cells/μL, and underscores the importance of ART adherence and prompt investigation of subacute neurological symptoms in HIV-infected individuals." (PMID 41209902, 2025). "ART-naïve people living with HIV who present with advanced HIV disease (AHD), as defined by the World Health Organization (WHO) (CD4 count ≤ 200 cells/mm3 or WHO stage III/IV), are at significantly higher risk of cryptococcal meningitis." (PMID 39854376, 2025). "Moreover, the severe CD4+ T cell deficiencies experienced by the vast majority of cryptococcal meningitis patients complicate current attempts to evaluate interactions between the host immune system and fungal cells, as the role of the adaptive immune system could well be extremely limited." (PMID 39470312, 2024). "Fluconazole can also cause DILI; therefore, fluconazole used for secondary prophylaxis of cryptococcal meningitis can be stopped if the CD4 count is > 200 cells/mm3." (PMID 38628909, 2024). "If the patient is on fluconazole for the intensive or consolidation phase of treatment of cryptococcal meningitis or if the CD4 count < 200 cells/mm3, seek advice from an infectious disease specialist." (PMID 38628909, 2024). "Prevalence of cryptococcal meningitis, CD4 count at diagnosis, treatment approach, and Outcome of treatment among participants (n = 405)." (PMID 38412200, 2024). "These vaccines have been shown to be protective in various mouse models of cryptococcal meningitis, including animals depleted of CD4+ T cells (reviewed in reference 48)." (PMID 37338404, 2023). "In immunological terms, cryptococcal meningitis is expected to be more prevalent at lower instead of higher levels of CD4+ T cells, given the worse immunosuppression and weaker infection controllability of individuals." (PMID 35130846, 2022). "Chen and Chen compared some indicators in the LN group infected with Cryptococcal meningitis with the uninfected group and found that the infected group had significantly decreased CD4+ T cells while SLEDAI was significantly higher." (PMID 36045722, 2022). "At the time of cryptococcal meningitis diagnosis, the median CD4 count was 60 (lower, upper quartiles 31, 112)." (PMID 33882845, 2021). "Generally, serious and life-threatening OIs, including CNS toxoplasmosis and cryptococcal meningitis are frequent among people having low CD4 count or percentages which increases their vulnerability to death." (PMID 32854692, 2020). "Despite a relatively low CrAg prevalence in PLWH with CD4 100–200 cells/mm3, using a low-cost screening test and prophylactic fluconazole would likely be cost-effective when compared to the high costs of cryptococcal meningitis and/or mortality." (PMID 31959112, 2020).
Cryptococcal meningitis (continued). "One study located in Uganda previously found that 9% of cryptococcal meningitis cases in PLWH presented in patients with a CD4 > 100 cells/mm3, and another study from South Africa found a prevalence of 12.5% in this group." (PMID 31959112, 2020). "While cryptococcal meningitis occurs in individuals with CD4 100–200 cells/mm3, there is limited evidence that CrAg screening predicts cryptococcal meningitis or mortality among this group with moderate immunosuppression." (PMID 31959112, 2020). "We sought to characterize the association of CrAg positivity by the standard of care serum enzyme immunoassay (EIA) with cryptococcal meningitis or death among PLWH with CD4 100–200 cells/mm3." (PMID 31959112, 2020). "In total, 7.9% (12/152) CrAg+ failed their preemptive fluconazole therapy and developed overt cryptococcal meningitis within 6 months of their CD4 blood draw." (PMID 30399034, 2019). "The phenotype of CD4+ T cell effector memory responses to Cryptococcus is associated with disease severity and outcome in HIV-associated cryptococcal meningitis." (PMID 31126019, 2019). "The case of cryptococcal meningitis with pachymeningitis and unilateral cavernous sinus syndrome occurred in a patient with CD4+ count of 338 cells/μL." (PMID 31061723, 2019). "Most cases of cryptococcal meningitis (CM) occur among persons with advanced immunosuppression (i.e. CD4+ T-cell [CD4] count <200 cells/μl)." (PMID 31830060, 2019). "Cryptococcal meningitis (CM) is an opportunistic fungal disease with a high mortality among HIV-positive patients with severe immunosuppression (CD4 count <100 cells/μl)." (PMID 29894509, 2018). "Cryptococcal meningitis (CM) was estimated to occur at a rate of 11% over 2 years in patients with CD4 counts <200 × 106/mL (6720 cases)." (PMID 29601494, 2018). "The provision of reflexed screening of early opportunistic HIV co-infections such as Cryptococcal meningitis with Cryptococcal antigen (CrAg) testing of all CD4 samples with counts less than 100 cells/μl is one such example." (PMID 29099874, 2017). "In the low CD4+ T cell group, 13 patients died, most of whom (11 patients) had serious cryptococcal meningitis." (PMID 29237413, 2017). "Cryptococcal meningitis is a major cause of mortality and morbidity in countries with high HIV prevalence, primarily affecting patients whose CD4 are < = 100 cells/μl." (PMID 28166254, 2017). "Overall, asymptomatic CrAg + participants fell in between the two populations and were notably more similar to cryptococcal meningitis survivors with regard to CD4 count (median 26 cells/μL, IQR: 9–59)." (PMID 28606065, 2017). "Cryptococcal meningitis and asymptomatic CrAg + participants had lower median CD4 counts (17 and 26 cells/μL, respectively) than the HIV-infected control cohort (233 cells/μL) as well as lower Karnofsky performance status (60 and 70 vs. 90, respectively)." (PMID 28606065, 2017). "In Kenya, viral load testing is now recommended for monitoring of patients on ART, replacing CD4 testing, which has since been reserved for baseline screening to identify patients eligible for cryptococcal meningitis prophylaxis (CD4 < 100)." (PMID 28577527, 2017). "Demographic data, cerebrospinal fluid pressure and CD4 count of 90 cryptococcal meningitis patients." (PMID 29568574, 2015). "Two (1.6 %) participants were CrAg-positive (CD4 cell counts 171 vs. 250 cells/μL), one of whom had clinically manifest cryptococcal meningitis at the time of testing." (PMID 26597840, 2015). "The mean CD4 count per mm3 for the major neurologic disorders identified was: cryptococcal meningitis = 55.5, cerebral toxoplasmosis = 66.3, tuberculous meningitis = 113.8 and bacterial meningitis = 204.4." (PMID 22490062, 2012). "The prevalence of cryptococcal meningitis was 14 of 93 (15.0%) patients with CD4 counts below 100 cells/mm3, six of 90 (6.7%) with a new diagnosis of HIV, and five of 48 (10.4%) who had been on ART for less than three months." (PMID 21988905, 2011).
Cryptococcal meningitis (continued). "The lower prevalence of cryptococcal meningitis in our population is likely due to higher median CD4 count (209 vs. 147 cells/mm3 at KCMC) as well as the inclusion of more patients on ART (50% vs. 22% at KCMC)." (PMID 21988905, 2011). "Predictors of cryptococcal meningitis by multivariate analysis included CD4 T cell counts of under 100 cells/mm3, altered mental status (GCS ≤ 14), fever (temperature > 37.5C) and neck stiffness, consistent with other studies." (PMID 21988905, 2011). "The median CD4 count of patients with cryptococcal meningitis was 68 cells/mm3 (IQR 54-87) and 14 (93.3%) had CD4 counts below 100 cells/mm3 (overall range 1-102 cells/mm3)." (PMID 21988905, 2011). "Not unexpectedly, clinically severe headache with CD4 counts of below 200 cells/mm3 was more likely to be due to cryptococcal meningitis; for those with CD4 counts of above 200 cells/mm3, severe headache was more likely to be due to sinusitis." (PMID 19765315, 2009). "In accordance with the previous studies, we found that PLHIV with lower CD4+ cell counts were more likely to be diagnosed with cryptococcal meningitis (t = 4.799, p = 0.001), esophageal candidiasis (t = 3.382, p = 0.001), PJP (t = 4.572, p = 0.000), and oral candidiasis (t = 4.273, p = 0.000)." (PMID 40943696, 2025). "Like the serum Cryptococcal Antigen test (CrAg) for cryptococcal meningitis, antigen tests for talaromycosis have the potential be used for targeted screening of high-risk patients, such as people with AHD and CD4 ≤ 200 cells/mL, to facilitate early treatment before the onset of symptoms." (PMID 40749024, 2025). "Moreover, the results of this study suggest that even with a CD4 concentration >50 cells/μL, we should still be vigilant against cryptococcal meningitis, especially when neurological symptoms exist." (PMID 41425969, 2025). "In addition to CD4 T cell count <100 cells/mm3, these signs and symptoms are predictive of cryptococcal meningitis." (PMID 39728839, 2024). "Our findings build on previous studies, which have individually reported the prevalence of CrAg and cryptococcal meningitis or death for PLWH with CD4 100–200 cells/mm3, but not their association." (PMID 31959112, 2020). "Current WHO guidelines (2018) recommend screening for cryptococcal antigen (CrAg) in HIV-infected persons with CD4+ T cell counts< 100 cells/μL, followed by pre-emptive antifungal therapy among CrAg positive (CrAg+) persons, to prevent cryptococcal meningitis related deaths." (PMID 32532212, 2020). "A previous meta-analysis established a pooled CrAg positivity prevalence of 2.0% for PLWH with CD4 100–200 cells/mm3, and recent data from sub-Saharan Africa suggests that at least 9% of cases of cryptococcal meningitis present in individuals with CD4 > 100 cells/mm3." (PMID 31959112, 2020). "In a similar manner, subgroup analyses in HIV-associated cryptococcal meningitis suggested that the greatest benefit of a short-course IFNγ adjuvant therapy was gained among patients with a lack of Cryptococcus-specific IFNγ/TNF CD4+ T cell responses." (PMID 29375567, 2017). "Additional genetic studies comparing DNA from patients with HIV-associated cryptococcal meningitis with that from population and CD4 cell count-matched individuals without evidence of cryptococcal infection are underway." (PMID 28334020, 2017). "In the normal CD4+ T cell group, only two patients died of cryptococcal meningitis." (PMID 29237413, 2017). "In a cryptococcal meningitis mouse model, CD4+ T cells were also found to mediate fungal clearance." (PMID 29237413, 2017). "However CD4 counts will continue to play an important role as a prognostic marker and in determining when to implement screening for conditions such as Cryptococcal meningitis." (PMID 27388763, 2016). "In addition to ART initiation, CD4 counts are also being used as a screening tool for reflex testing to screen for and prevent Cryptococcal meningitis in patients with a CD4 count <100 cells/μl." (PMID 26208867, 2015).
Cryptococcal meningitis (continued). "Patients with cryptococcal meningitis presented with typical symptoms, and universal screening with a serum cryptococcal antigen assay at the time of admission did not seem to improve diagnosis rates compared with traditional, symptom and CD4 count guided testing." (PMID 21988905, 2011). "Cryptococcal meningitis, an infection of the brain, spinal cord, and cerebrospinal fluid (CSF), is a major contributor to death among people with advanced HIV disease, with CD4+ T cells less than 100 cells/mm3." (PMID 39928682, 2025). "Cryptococcal meningitis should be considered in individuals diagnosed with human immunodeficiency virus (HIV) infection and presenting with a cluster of differentiation 4 (CD4)-helper T cell count below 100 cells/ml." (PMID 38590504, 2024). "Cryptococcal meningitis primarily affects people with very advanced HIV disease, typically with a CD4 count less than 100 cells/μL." (PMID 38106376, 2023). "The sample collection consisted of sera from HIV-positive (CD4+ T cells <250 cells/μL, n=28) and HIV-negative (n=16) Colombian cryptococcal meningitis (CM) patients as well as healthy Colombian blood donors (n=15)." (PMID 34367172, 2021). "Cryptococcal antigen (CrAg) screening with fluconazole prophylaxis has been shown to prevent cryptococcal meningitis and mortality for people living with HIV (PLWH) with CD4 < 100 cells/mm3." (PMID 31959112, 2020). "We present a patient with cryptococcal meningitis in an HIV-negative patient with low MBL and low naïve CD4 count suffering a chronic relapsing meningo-encephalitis with relatively mild symptoms for around 2 years." (PMID 31615425, 2019). "Given the positive association of the circulating frequencies of CSF infiltrating leukocytes and peripheral circulating CD4+ T cells and CD8+ T cells, the circulating immunocytes is an important determinant or source of CSF infiltrating leukocytes in CSF with cryptococcal meningitis." (PMID 39928682, 2025). "Cryptococcal meningitis, esophageal candidiasis, oral candidiasis, and PJP predominantly occurred in individuals with CD4+ counts below 200 cells/mm3, while increased CD4+ levels were found in individuals with dermatophytosis, onychomycosis, and Pityriasis/Tinea versicolor." (PMID 40943696, 2025). "Participants presenting with cryptococcal meningitis while taking ART had similar demographics to those not on ART but had higher baseline CD4 counts and lower baseline fungal burdens in both the AMBITION study and combined dataset." (PMID 40608053, 2025). "Systemic multiple OIs was the most important variable, followed by unexplained infections, NADEs, baseline CD4 cell count, admission to the ICU, baseline viral load, cryptococcal meningitis, multiple OIs in the central nervous system (CNS), and systemic disseminated tuberculosis." (PMID 38249414, 2023). "None (0/29) were diagnosed with cryptococcal meningitis in the 3 months following CD4 testing and reflex CrAg screening, and 28/29 were alive at the completion of follow-up." (PMID 33087436, 2020). "Co-occurrence of Kaposi’s sarcoma and cryptococcal meningitis in the setting of HIV infection is rare, as illustrated by an unusual case of both diseases in a South African cohort of 127 individuals with HIV infection and low CD4 count." (PMID 30867046, 2019). "The CD4+ T cell median count was 35 cells/mL (IQR 12–58), and only four patients had CD4+ T cell counts >100 (three of them had disseminated histoplasmosis and one cryptococcal meningitis)." (PMID 30205586, 2018). "In comparison, the antigen prevalence was 6% using the LA in a cohort with CD4 cell counts ≤100 cells/μL and no prior cryptococcal meningitis drawn from the same patient population between 2002 and 2005." (PMID 26565007, 2016).
Cryptococcal meningitis (continued). "We prospectively enrolled 25 asymptomatic, antiretroviral therapy (ART)-naïve CRAG+ Ugandans with CD4<100 cells/mcL who received pre-emptive fluconazole treatment (CRAG+ cohort) and 189 ART-naïve Ugandans with symptomatic cryptococcal meningitis treated with amphotericin (CM cohort)." (PMID 23251485, 2012). "Another systematic review that involved 31 studies of which 21 (68%) were from Africa showed that among those with CD4 count < 100 cells/mm3, the incidence of cryptococcal meningitis was 21.4% without preemptive fluconazole compared to 5.7% with preemptive fluconazole." (PMID 39854376, 2025). "Itraconazole is not recommended to treat cryptococcal meningitis but it may be used as a prophylaxis against cryptococcal meningitis, particularly in patients with CD4 counts <100 cells/μL." (PMID 37237787, 2023). "In those with CD4 100–200 cells/mm3 (N = 209), two of four (IR: 58.8 per 100 person-years) CrAg positive participants and 11 of 205 (IR: 5.6 per 100 person-years) CrAg negative participants died, and none developed cryptococcal meningitis." (PMID 31959112, 2020). "But, CSF leukocytes counts, CSF cryptococcal log10 CFUs, CD4+ T cells, CD8+ T cells, CSF protein, and blood leukocytes counts, these variables did not independently predict survival with cryptococcal meningitis among all participants with (Model 2 and S7)." (PMID 39928682, 2025). "From this clinical case, there is evidence that both cryptococcal meningitis and gastric Kaposi’s sarcoma can coexist at any stage of HIV infection, and irrespective of the CD4 count." (PMID 30867046, 2019). "Low CSF concentrations of IFN-γ and a blood CD4+ T-cell phenotype characterized by a lack of IFN-γ and TNF-α production have been observed in HIV-infected individuals who died from cryptococcal meningitis." (PMID 26768248, 2016). "In low-resource settings where antiretroviral therapy is not universally available and the burden of cryptococcal meningitis is very high, the WHO has recommended primary fluconazole prophylaxis for all HIV patients with a CD4 count < 100 cells/μL as this has been demonstrated to improve survival." (PMID 29371581, 2017).